KIF20A (kinesin family member 20A)
Diseases named in the same sentence as KIF20A in open-access papers (continued):
Sharing a sentence is not in itself a finding about the gene and the disease.
cancer (continued). "We previously discussed the relation of KIF20A with ferroptosis; however, this gene mediates the spindle formation during mitosis and its overexpression is related to both, cancer development and a poor overall survival of patients." (PMID 40176904, 2025). "We have highlighted that KIF20A is upregulated in various cancers and is strongly correlated with poor overall survival." (PMID 40600015, 2025). "As a member of the kinesin family, KIF20A contributes to cancer progression by regulating cell division." (PMID 40822284, 2025). "With ongoing research and clinical development, KIF20A stands as a beacon of hope for improving cancer treatment outcomes and offering patients a brighter future." (PMID 39272816, 2024). "By effectively inhibiting KIF20A, Paprotrain disrupts the autocrine activation mechanisms of the androgen receptor (AR), a key driver of cancer proliferation in prostate cells that have become resistant to traditional androgen-deprivation therapies." (PMID 39272816, 2024). "The promising outcomes observed in trials thus far offer a glimpse into the potential of KIF20A as a cornerstone in the fight against cancer, heralding a new chapter in the quest for more effective, targeted, and personalized cancer therapies." (PMID 39272816, 2024). "The future of KIF20A-targeted cancer therapy lies in the intersection of innovative research, collaborative efforts across disciplines, and a commitment to translating scientific discoveries into clinical advances." (PMID 39272816, 2024). "This review aims to consolidate the existing knowledge on KIF20A within the cancer research field, detailing its crucial role in tumorigenesis and its potential to enhance the efficacy of cancer diagnostics, prognostics, and treatments." (PMID 39272816, 2024). "The expression of KIF20A has been highlighted across various studies as a pivotal factor in the prognosis and progression of numerous cancers." (PMID 39272816, 2024). "The recent advances in molecular biology have emphasized KIF20A’s critical functions in cellular processes and its abnormal expression in different cancers." (PMID 39272816, 2024). "KIF20A is highly expressed in cancer cells, making it a promising therapeutic target for various cancers." (PMID 39902297, 2024). "By concentrating on the significant potential of KIF20A as both a direct target for inhibitors and an antigen in cancer vaccines, this review sets a foundation for future research aimed at harnessing KIF20A for effective cancer treatment." (PMID 39272816, 2024). "Aberrant expression of the Mklp2-encoding KIF20A gene and the RepoMan-encoding CDCA2 gene have been observed in a variety of cancers and significantly correlates with survival outcomes." (PMID 38806145, 2024). "The emerging evidence supporting the efficacy of KIF20A-targeted immunotherapies, particularly peptide vaccines, heralds a new era in the personalized treatment of cancer, offering hope for improved patient outcomes." (PMID 39272816, 2024). "Deeper insights into the biology of KIF20A, including its role in cancer progression and interaction with other cellular proteins, will inform the development of more effective therapeutic strategies." (PMID 39272816, 2024). "To characterize possible genetic or epigenetic alterations of KIF20A in tumors, we first studied in silico a set of pan-cancer via cBioportal database." (PMID 39624268, 2024). "The collective insights from these studies accentuate the pivotal role of KIF20A as a versatile and effective target in cancer immunotherapy." (PMID 39272816, 2024). "The exploration of KIF20A within the context of cancer biology and therapy presents a promising frontier in the ongoing battle against cancer." (PMID 39272816, 2024). "As we continue to explore the therapeutic potential of targeting KIF20A in cancer, overcoming these challenges and leveraging new technologies and insights will be critical." (PMID 39272816, 2024).
cancer (continued). "In the landscape of cancer immunotherapy, KIF20A has emerged as a prominent target across various studies, indicating its pivotal role as a novel TAA with significant therapeutic potential." (PMID 39272816, 2024). "Next, we examine the oncogenic impact of Paprotrain, a targeted KIF20A inhibitor, on diverse cancer cell models." (PMID 39272816, 2024). "The structural domains of KIF20A facilitate its roles in microtubule dynamics and vesicle transport, which are pivotal in cellular homeostasis and can contribute to cancer development when dysregulated." (PMID 39272816, 2024). "KIF20A, a mitotic kinesin, plays a significant role in cell division and intracellular transport and is notably overexpressed in various cancers, making it a potential target for cancer therapy." (PMID 39272816, 2024). "Advancements in cancer immunotherapy have leveraged KIF20A as a novel antigen to develop peptide vaccines, enhancing the immune system’s ability to target cancer cells." (PMID 39272816, 2024). "This review focuses on the current advancements in the development of inhibitors and the application of kinesin family member 20A (KIF20A) as a cancer immunotherapy target." (PMID 39272816, 2024). "Nevertheless, comprehensive studies are required to better understand the broader implications of KIF20A inhibition on normal cells, as well as to determine its therapeutic potential across different cancer types." (PMID 39272816, 2024). "By focusing on the molecular behavior and clinical implications of KIF20A across various cancers, this review underscores its importance in the era of precision medicine, paving the way for more targeted and effective cancer therapies." (PMID 39272816, 2024). "Based on the statistical analyses of the PPI network of upregulated genes, AURKA, AURKB, TTK, MELK, and KIF20A were also involved in module 1, indicating their importance both in primary tumorigenesis and cancer progression." (PMID 37231064, 2023). "KIF20A is closely associated with a series of tumors, proteomic mapping displayed that KIF20A determined the aggregation of centrosomes in cancer cells, leading to apoptosis." (PMID 36927438, 2023). "KIF20A is upregulated in a variety of malignancies, and its depletion reduces tumour cell viability, making it a target and biomarker for cancer therapies." (PMID 37726093, 2023). "In this review, we summarized the expression of KIF20A in tumors and the mechanisms of KIF20A regulating cancer, organized all clinical trials related to KIF20A." (PMID 36798768, 2023). "In summary, KIF20A was highly expressed in tumors, promoted proliferation, migration, and invasion of cancer." (PMID 36798768, 2023). "We used GEPIA to explore the expression of KIF20A in normal and cancer tissues, results shows that KIF20A highly expressed on almost all kinds of cancers." (PMID 36798768, 2023). "A total of 75 KIF20A epitopes have specifically been identified on cancer cells, with 4 epitopes described on EOC." (PMID 36768616, 2023). "In this review, we summarized all the cancer that highly expressed KIF20A, described the role of KIF20A in cancer." (PMID 36798768, 2023). "The other hub genes (e.g., YBX1, OLA1, TRMT10C, and KIF20A) also play a key role in the development and prognosis of the pan-cancer section." (PMID 35720008, 2022). "Studies have shown that the overexpression of RRM2 and KIF20A usually accompanies the occurrence of cancer and plays a malignant role in cancer." (PMID 34787756, 2022). "Based on the cancer genome atlas (TCGA) and genome-tissue expression (GTEx) analyses, KIF20A has been identified as the hub gene." (PMID 36619388, 2022). "Comparatively, the pivotal role of the kinesin family member 20A (KIF20A) has been extensively explored in cancer." (PMID 36096734, 2022). "For instance, KIF20A is mainly involved in cellular proliferation, migration, invasiveness, and angiogenesis and is significantly upregulated in different types of cancers." (PMID 35204562, 2022).
cancer (continued). "HMMR and KIF20A are important regulators of mitosis and exhibit oncogenic properties in various cancers through multiple mechanisms." (PMID 34556750, 2021). "Our data obtained from Atoh1-CreER; Kif20afl/fl single and Atoh1-CreER; Ptcfl/fl; Kif20afl/fl double-knockout mice together showed that KIF20A functions similarly in normal and cancer-initiating GNPs to maintain their proliferative potential." (PMID 33976373, 2021). "Previous literature clearly indicates that HMMR and KIF20A function as oncogenes in many types of cancers." (PMID 34595101, 2021). "By altering the expression of eukaryotic cytoskeleton proteins, which play important roles in cancer progression and cytoskeleton modulation, KIF20A is sensitive to alterations along with mechanical loadings." (PMID 33936212, 2021). "The expression and activity of KIF20A participate in the regulation of intracellular transport and cell division, playing an important role in the occurrence and development of cancer." (PMID 33941190, 2021). "On the other hand, in silico studies of cancer expression data or expression analyses of clinical samples showed that KIF20A expression is positively correlated with poor prognosis of patients in different types of cancers." (PMID 33976373, 2021). "The role of CD44 and KIF20A in tumors has been well studied, and they are upregulated in a variety of cancers." (PMID 33816274, 2021). "The silencing of KIF20A also enhances the sensitivity of cancer cells to genistein inhibition whereas KIF20A overexpression markedly reduces genistein-stimulated cell viability and G2/M arrest." (PMID 34336089, 2021). "This study explores the role of FOXM1 in PCa docetaxel resistance and its association with kinesin family member 20 A (KIF20A), which is known to promote therapeutic resistance in some cancers." (PMID 33292277, 2020). "Several studies indicate KIF20A is transcriptionally regulated by FOXM1 in certain cancer cells, and that their expression is consistently elevated after treatment with paclitaxel." (PMID 33292277, 2020). "The results showed that patients with cancer and high KIF20A expression had a significantly poor OS compared to those with low KIF20A expression (HR = 1.77, 95% CI = 1.57–1.99, P < .001)." (PMID 31725680, 2019). "High expression of KIF2 and KIF20A in human cancer was significantly correlated with worse prognosis and unfavorable clinicopathological features, suggesting that these 2 KIF members can be used as prognostic biomarkers for different types of tumors." (PMID 31725680, 2019). "KIF4A, KIF14 and KIF20A are shown to be overexpressed across many human cancer types suggesting a link between expression levels and overall survival." (PMID 30991738, 2019). "Overall, high expression of KIF2A and KIF20A was associated with shorter OS, and these two KIF members can serve as independent factors for predicting the survival outcomes of patients with cancer." (PMID 31725680, 2019). "As a transcription factor, FOXM1 has many target genes including KIF20A, CENPF, CCNB1, MYC, NIMA-related kinase 2, MMP2, MMP9, and S-phase kinase-associated protein 2 that are implicated in cancer initiation, progression, or drug resistance." (PMID 31072351, 2019). "The expression mechanisms of KIF2A and KIF20A are different and complicated in various types of cancer." (PMID 31725680, 2019). "Our findings were highly consistent with previous studies about the prognostic impact of KIF20A in other cancers." (PMID 30105795, 2018). "Our in vitro analyses demonstrated that migration and invasion of cancer cells were significantly reduced by silencing KIF20A." (PMID 28081138, 2017). "Here, we demonstrated that down-regulation of KIF20A, thereby disruption of the normal process of cytokinesis and induction of mitotic arrest, is among mechanisms of action of fisetin on cancer cells." (PMID 28052097, 2017).
cancer (continued). "Our data also suggest that FOXM1 and KIF20A can be useful predictive biomarkers, in addition to being therapeutic targets for cancer treatment and for tackling taxane resistance in cancer." (PMID 25961928, 2016). "We propose that the trial of the cocktail vaccine of these high immunogenic peptides including KIF20A-66 will provide with better treatment and cure for cancer." (PMID 24237633, 2013). "Next, the capacity of these CTLs to kill human cancer cell lines expressing both KIF20A and HLA-A2 was examined." (PMID 21179034, 2011). "Western blot analysis revealed expression of the KIF20A protein in various HLA-A2+ cancer cell lines tested, except for SKHep1 (right)." (PMID 21179034, 2011). "On the other hand, the expression of the KIF20A gene was detected in almost all pancreatic and other HLA-A2-positive cancer cell lines tested (left)." (PMID 21179034, 2011). "Furthermore, the expression of KIF20A correlates with immune cell infiltration and the expression of immune checkpoint molecules, impacting the efficacy of immunotherapy in various cancers." (PMID 41646843, 2026). "Furthermore, some Kinesin family members, like KIF2C, KIF20A, KIF18A, and KIF15, have been linked to cancer progression and potentially to resistance against hormone-based therapies." (PMID 40869915, 2025). "KIF20A suppresses cancer cell proliferation, migration, and invasion." (PMID 40822284, 2025). "Several studies have investigated the role of KIF20A in cancer." (PMID 41392981, 2025). "Kinesin family member 20A (KIF20A) is a member of the kinesin superfamily, a group of molecular motors which are vital for numerous cellular functions, such as cell proliferation, vesicular transport, and cancer progression." (PMID 39624268, 2024). "KIF20A was significantly upregulated in pan-cancer (including HCC)." (PMID 39624268, 2024). "In the TCGA cohorts, we noticed an extensive enrichment of KIF20A in pan-cancer." (PMID 39624268, 2024). "To elucidate the involvement of KIF20A in the development of human cancers, we performed a pan-cancer analysis of KIF20A expression using the TCGA dataset, which provides a potential resource for exploring the molecular characteristics of diverse cancer types." (PMID 39624268, 2024). "The study elucidated that epitopes from KIF20A and other TAAs elicited significant immune responses in patients, suggesting their utility in devising immunotherapeutic strategies for this challenging cancer type." (PMID 39272816, 2024). "In recent years, studies have confirmed that KIF20A is highly expressed in cancer." (PMID 39045407, 2024). "The ability of KIF20A-derived peptides to elicit robust immune responses across different cancer types, coupled with their tolerability and potential for improved patient outcomes, paves the way for a new era of cancer treatment." (PMID 39272816, 2024). "These combined characteristics of KIF20A’s domains elucidate its multifaceted roles in cellular processes, highlighting its potential as a therapeutic target, especially considering its upregulation in various cancers." (PMID 39272816, 2024). "Understanding the dynamic between FOXM1 and FHRE within the KIF20A promoter could pave the way for novel cancer treatment modalities, particularly where the dysregulation of KIF20A contributes to disease progression." (PMID 39272816, 2024). "More and more studies focus on the relationship between KIF20A and cancer." (PMID 36798768, 2023). "Overall, the relationship between KIF20A and cancer suggests that KIF20A may be a potential therapeutic target for cancer treatment." (PMID 37310408, 2023). "KIF20A is a critical kinesin for cell division and a promising anti-cancer drug target." (PMID 37726093, 2023). "In summary, KIF20A was a potential cancer therapeutic target." (PMID 36798768, 2023). "Recently, studies proved that KIF20A was highly expressed in cancer." (PMID 36798768, 2023). "The overexpression of KIF20A can contribute to cancer cell proliferation, migration, and invasion." (PMID 37744243, 2023).
cancer (continued). "Therefore, our findings elucidate a hitherto unexplored mechanism of KDELR2 and KIF20A in BCa, linking a Golgi‐ER traffic transport protein to a critical kinesin during cancer progression." (PMID 36096734, 2022). "In addition, cancer cells overexpressing KIF20A can be recognized by host immune system and hence KIF20A-derived peptides can be used as immunotherapeutic agents." (PMID 32752229, 2020). "Extensive research has revealed the pivotal role of kinesin family member 20A (KIF20A) in cancer." (PMID 33232285, 2020). "Therefore, here we aimed to investigate the role of KIF20A in ccRCC and thus provide new directions for future cancer research." (PMID 33232285, 2020). "The molecular mechanism of KIF20A in cancer is still unclear." (PMID 31093305, 2019). "The abnormal expression of KIF20A may lead to abnormal cell division, which can then lead to chromosomal aneuploidy and genomic instability in cancer." (PMID 31093305, 2019). "Thus, further large-scale, high-quality, and better designed multi-center studies should be performed to clarify the function of KIF2A and KIF20A in various human cancers." (PMID 31725680, 2019). "Subgroup analysis of the pooled HR of OS with KIF2A and KIF20A expression in patients with cancer." (PMID 31725680, 2019). "In addition, in the field of oncology, the expression level of KIF20A has been found to be upregulated in several types of cancer, including breast, pancreatic, lung, and bladder cancer." (PMID 31841120, 2019). "Therefore, we performed this meta-analysis of eligible studies to further examine the prognostic significance of KIF2A and KIF20A in different types of human cancers." (PMID 31725680, 2019). "Background/Aims: Kinesin family member 20A (KIF20A) is upregulated in multiple cancers and plays important roles in promoting malignant behavior, whereas its exact role in CRC remains unknown." (PMID 31841120, 2019). "Cancer cells overexpressed KIF20A can be recognized by hosts to initiate immune response, thereby KIF20‐derived peptides could be used as a novel immunotherapy agent." (PMID 30105795, 2018). "Numerous studies have shown KIF20A may play a critical role in the development and progression of cancer." (PMID 28081138, 2017). "Knockdown of Kif20a suppressed the proliferation of different cancer cell lines." (PMID 28659168, 2017). "Indeed, we have examined several peptides derived from a variety of cancer-testis antigens that have the oncogenic activity, including KIF20A, DEPDC1, MPHOSPH1, URLC10(LY6K),TTK, KOC1(IMP3), CDCA1, RNF43, and TOMM34." (PMID 24237633, 2013). "Peptide-reactive human CTLs were generated from peripheral blood mononuclear cells of HLA-A2+ healthy donors by in vitro stimulation with the three peptides, and those CTLs successfully exhibited cytotoxic responses to cancer cells expressing both KIF20A and HLA-A2." (PMID 21179034, 2011). "Therefore, the lactate-induced E2F1 activation, with its downstream regulation of KIF20A, contributes to the carcinogenic cascade, fostering the migration and metastasis of cancer cells and delineating a lactate-E2F1-KIF20A pathway integral to cancer progression." (PMID 39272816, 2024). "Therefore, understanding and potentially targeting KIF20A’s role in these processes could be crucial for developing new therapeutic strategies against cancer." (PMID 39272816, 2024). "Aberrant expression of KIF20A might result in abnormal cellular behaviors in cancer cells." (PMID 36619388, 2022). "Interestingly, our results are similar to previous studies, in which KIF20A may be a key molecule influencing cancer development." (PMID 31565099, 2019). "Third, the cut-off values, which were used to distinguish between high and low groups of KIF2A/KIF20A expression, were difficult to define by the uniform criteria because of the diversity of different cancer types, which may have led to some heterogeneity in the results." (PMID 31725680, 2019).